MTOR (mechanistic target of rapamycin kinase)
Diseases named in the same sentence as MTOR in open-access papers (continued):
Sharing a sentence is not in itself a finding about the gene and the disease.
subependymal giant cell astrocytoma (continued). "For instance, everolimus, an mTOR-inhibitor (mTORi), has been found particularly efficient for treating subependymal giant cell astrocytomas (SEGA), angiomyolipomas (AML), facial angiofibromas, and epilepsy in TSC patients, if used continuously." (PMID 37386496, 2023). "It has been reported that everolimus, an mTOR inhibitor, presents significant clinical efficacy in improving subependymal giant cell astrocytoma (SEGA), angiomyolipoma (AML), lymphangioleiomyomatosis (LAM), and facial angiofibroma caused by TSC 7-9." (PMID 37786437, 2023). "The effectiveness of oral mTOR inhibitors for the treatment of TSC-related manifestations is established for subependymal giant cell astrocytoma (SEGA), renal angiomyolipoma, lymphangioleiomyomatosis (LAM), epilepsy, cardiac rhabdomyoma, and skin lesions." (PMID 36104799, 2022). "Next, to investigate whether the activation of Src/ERK/Akt/mTOR kinases were key elements of the leptin induced proliferation in 1321N1 astrocytoma cells, they were incubated in the absence or presence of an optimal concentration of human recombinant leptin (0.5 μM) at different times." (PMID 28249041, 2017). "Based on double-blinded, placebo-controlled, randomised, clinical trials that confirmed its safety and efficacy, the mTOR-inhibitor everolimus (Votubia®) was approved in Europe in 2011 for the treatment of subependymal giant cell astrocytoma (SEGA) and renal angiomyolipoma." (PMID 33833726, 2021). "Widely used in the treatment of subependymal giant cell astrocytoma (SEGA) in patients with TSC, including children <2 years of age, mTOR inhibitors have been shown to be beneficial for tumor control and also seizure control in this patient population." (PMID 33643212, 2021). "In our study, we found that NSCLC patients had high positive expression of p-mTOR and p-eIF4E proteins, which supports our previous findings in NPC and astrocytomas." (PMID 32023262, 2020). "For acutely symptomatic subependymal giant cell astrocytoma (SEGA) in the brain, surgical resection is the recommended first-line therapy, while medical therapy with mTOR inhibitors is recommended for growing but asymptomatic SEGA." (PMID 30760308, 2019). "Compared with the placebo, mTOR inhibitors significantly reduced tumor volume in both angiomyolipoma (AML) (RR = 24.69, 95% CI = 3.51,173.41, P = 0.001) and subependymal giant cell astrocytoma (SEGA) (RR = 27.85, 95% CI = 1.74,444.82, P = 0.02)." (PMID 30760308, 2019). "Everolimus also has an established role in the treatment of two rare conditions: renal angiomyolipomas associated with TSC or lymphangioleiomyomatosis, as well as TSC-related subependymal giant cell astrocytoma (SEGA), both characterized by constitutive activation of the mTOR pathway." (PMID 24782981, 2014). "Several laboratory studies and case reports have suggested that mTOR inhibition leads to the shrinkage or stabilization of renal AML, LAM, facial angiofibroma and subependymal giant cell astrocytoma." (PMID 24612911, 2014). "Further studies are required to investigate the utility of mTOR pathway inhibitors in the treatment of PXA, though it has proven efficacious in the treatment of sub-ependymal giant cell astrocytomas, another rare pediatric brain tumor." (PMID 23592488, 2013). "A more recent study reported that PIK3R1 is uniquely overexpressed in IDH1-mutant grade 4 astrocytoma, indicating that combined targeting of the PI3K/AKT/mTOR pathway and the immune system may be necessary for effective treatment in this subtype." (PMID 40504311, 2025). "With regard to mTOR inhibitors, everolimus and sirolimus are two agents with Food and Drug Administration approval to treat various systemic manifestations of TSC, including subependymal giant cell astrocytomas, angiomyolipomas and lymphangioleiomyomatosis." (PMID 38540325, 2024).
subependymal giant cell astrocytoma (continued). "These clinical and preclinical findings support the role of PDGFRA gene alterations and downstream multiple signaling pathways, including PI3K/AKT/mTOR pathway and RAS/RAF/MEK/ERK pathway, in promoting progression of not only IDH1-mutant, but also IDH2-mutant astrocytoma." (PMID 38012788, 2023). "Similarly, in the context of the IDH mutant astrocytoma, the tumor with higher AUP1 was significantly correlated with PI3K-AKT-MTOR pathway (EGFR, PDGFRA, TSC2, MTOR), and autophagy signaling (ATG4B)." (PMID 37029364, 2023). "mTOR inhibitors (sirolimus, everolimus) are used in the clinical practice of TSC patients for the treatment of enlarging subependymal giant cell astrocytomas, renal angiomyolipomas > 4 cm, or > 3 cm and growing rapidly, symptomatic cardiac rhabdomyomas and facial angiofibromas." (PMID 32326947, 2020). "Based on the regulatory role of the mTOR pathways, mTORC1 inhibitors support the possibility of treating TSC patients based on the physiological pathogenesis, including renal angiomyolipoma, giant cell subependymal astrocytoma, and lymphatic vessel leiomyomatosis." (PMID 35928867, 2022). "The TSC negatively regulates the mTOR pathway, resulting in typical subependymal giant cell astrocytoma (SEGA) in 20% of all patients, and only a small number of reports of SEGA without the clinical features of TSC exist." (PMID 34828788, 2021).
psoriasis (92 papers, 2015 to 2025). An autoimmune condition characterized by red, well-delineated plaques with silvery scales that are usually on the extensor surfaces and scalp. "mTOR pathway dysregulation can cause various conditions, including psoriasis, acne, and atopic dermatitis." (PMID 39861084, 2024). "Dysregulation of the PI3Kk/Akt/mTOR pathway is observed in skin cancer, psoriasis, and AD, and is associated with uncontrolled and excessive proliferation of inflammatory skin cells." (PMID 38533495, 2024). "BCAA’s association with psoriasis mainly lies in their involvement as activators of the mTOR pathway promoting IR, oxidation and inflammation." (PMID 37405259, 2023). "In psoriasis, uncontrolled keratinocyte proliferation is associated with activation of the mTOR pathway and involves different Th-1, Th-17, and Th-22 immune cells, and their effector cytokines (e.g., IL-1β, IL-6, IL-17A, TNF-α) that act on keratinocytes." (PMID 37371141, 2023). "Dysregulation of mTOR signaling underlies the pathogenesis of skin diseases, including psoriasis and skin cancer." (PMID 35938153, 2022). "Several lines of evidence have demonstrated that abnormal mTOR signaling activation are associated with psoriasis." (PMID 35938153, 2022). "Dysregulated mTOR signaling is associated with the development of various skin disorders, such as impaired wound healing, psoriasis, and skin cancer." (PMID 35938153, 2022). "The PI3K/Akt/mTOR pathway regulates both innate and adaptive immune responses and is linked to the Th1/Th2/Th17 disequilibrium associated with psoriasis etiology." (PMID 35163615, 2022). "Since psoriasis is associated with the hyper-proliferation of keratinocytes, growing studies demonstrated the mTOR pathway is related to the occurrence of psoriasis." (PMID 36498953, 2022). "Genomic analyses have shown that genome-wide association studies (GWAS) and single-cell sequencing technologies have revealed some remarkable phenomena, and psoriasis is significantly associated with aberrant activation of signaling pathways such as PI3 K/AKT/mTOR, JAK-STAT and WNT." (PMID 41293553, 2025). "In addition to this, IL-17A can also inhibit autophagy by activating the PI3K/Akt/mTOR pathway, which in turn promotes psoriasis-associated inflammation." (PMID 39559368, 2024). "Recent studies have shown that the PI3K-Akt-mTOR signaling pathway that is important in cell metabolism, growth, and survival is dysregulated and linked to the pathophysiology of diverse skin diseases including psoriasis." (PMID 36741386, 2022). "In addition to aberrant cytokine production, psoriasis is associated with activation of the Akt/mTOR pathway." (PMID 36741386, 2022). "Activation of the PI3K/Akt/mTOR and associated signaling cascade has been linked to psoriasis pathophysiology such that released proinflammatory cytokines aberrantly induce mTOR activation that subsequently promote psoriatic lesions and epidermal keratinocyte hyperplasia." (PMID 36741386, 2022). "Upregulation of mTOR signaling proteins has also been reported in psoriasis, in association with enhanced proliferation, defective keratinocyte differentiation, senescence-like growth arrest, and resistance to apoptosis, accounting for major parts of the overall disease phenotypes." (PMID 33996865, 2021). "In this context, the modulation of PI3K/Akt/mTOR activity is known to promote epidermal hyperplasia and exert distinct regulatory roles in the same innate immune cells that are implicated in the immunopathogenesis of psoriasis." (PMID 31540162, 2019). "Second, mechanisms underlying heightened translation in psoriasis lesions may be broader than currently understood, involving some proteins besides canonical mTOR targets (e.g., ribosomal subunits and translation factors)." (PMID 26251673, 2015).
psoriasis (continued). "Delphinidin has been demonstrated to inhibit the PI3K/Akt/mTOR signaling pathway in imiquimod-induced psoriasis, which is frequently upregulated in psoriatic lesions and contributes to the excessive proliferation of keratinocytes." (PMID 40690118, 2025). "MCEO acts by inhibiting PI3K/Akt/mTOR and p38MAPK signaling pathways, which are involved in the inflammation and pathogenesis of psoriasis." (PMID 40917836, 2025). "In this study, we found that trifolirhizin inhibited the decrease of AMPK phosphorylation and the increase of mTOR phosphorylation in epidermal tissue in psoriasis-like skin lesions and keratinocytes." (PMID 40862458, 2025). "Understanding the role of mTOR in psoriasis, psoriatic arthritis, and cardiovascular disease provides insight into the potential treatment avenues and sheds light on the complex interplay of the immune and metabolic pathways in these conditions." (PMID 38928483, 2024). "We demonstrated that limonin mediates mTOR inhibition via AMPK activation in an in vitro model of IL-17-stimulated psoriasis-like inflammation." (PMID 39765869, 2024). "The sustained activation of mTOR is a key element in psoriasis pathogenesis, leading to an uncontrolled proliferation of cytokines." (PMID 38928483, 2024). "Our findings suggest that limonin plays an important role in attenuating the inflammatory response in psoriasis by inhibiting mTOR and mTORC1 activity." (PMID 39765869, 2024). "The PI3K/Akt/mTOR pathway, known for its role in cell growth, proliferation, and metabolism, has emerged as a potential therapeutic target in psoriasis." (PMID 38928483, 2024). "In an imiquimod (IMQ)-induced mouse model of psoriasis, CR treatment attenuated the pathogenesis of psoriasis phenotypes, accompanied by a reduced activation of mTOR signaling in the psoriatic skin." (PMID 39371941, 2024). "TRIM22 enhances keratinocyte inflammation and inhibits autophagy through activation of the PI3K/Akt/mTOR pathway, which in turn promotes psoriasis." (PMID 39559368, 2024). "Rapamycin is a well-established mTOR inhibitor that underscores the critical role of the mTOR signaling pathway in the pathogenesis of psoriasis." (PMID 39765869, 2024). "This amelioration of psoriasis-like symptoms in CR mice was accompanied by a reduction in mTOR signaling activation in psoriatic skin." (PMID 39371941, 2024). "In psoriasis, mTOR plays an important role in the regulation of energy metabolism and is a key signaling pathway that regulates the activation and proliferation of immune cells and keratinocytes." (PMID 39765869, 2024). "This review explores the relevance of mTOR in psoriasis pathophysiology, focusing on its involvement in cutaneous and atheromatous plaque proliferation, psoriatic arthritis, and cardiovascular disease." (PMID 38928483, 2024). "These agents have been shown to mitigate psoriatic lesions in the imiquimod (IMQ)-induced psoriasis mouse model by suppressing the PI3K/Akt/mTOR pathway." (PMID 37935955, 2023). "Using HaCaT cells, it was shown that metformin inhibits the expression of inflammatory cytokines (IL-6 and TNF-α) and downregulates the growth factor VEGF thus inhibiting the inflammatory response in psoriasis by inhibiting mTOR." (PMID 37371141, 2023). "The mTOR pathway is also activated in psoriasis patients’ Treg and peripheral blood mononuclear cells." (PMID 37405259, 2023). "A recent report has confirmed that IL-17 stimulated keratinocytes activated PI3K/AKT/mTOR signaling in psoriasis." (PMID 36744265, 2023). "Several recent studies have highlighted that among the many signaling networks implicated in psoriasis, deregulation of the PI3K/Akt/mTOR and associated signaling pathways critically contribute to disease initiation and progression." (PMID 37371141, 2023). "Another mTOR inhibitor everolimus, a rapamycin analog, has also shown potential in treating psoriasis alone or in combination with tacrolimus in a patient with severe refractory psoriasis." (PMID 37371141, 2023).
psoriasis (continued). "For example, PSORI-CM02 induces autophagy by inhibiting the PI3K/Akt/mTOR pathway, thereby alleviating the development of psoriasis, an inflammatory skin disease." (PMID 36272879, 2023). "Apart from the main influence of ScF on psoriasis treatment via the mTOR signaling and Th17 differentiation pathways, ScF also demonstrated therapeutic effects via another mechanism." (PMID 37495626, 2023). "In summary, we propose that ScF—a combination of sericin extraction and 2D flexible, photocrosslinked fibroin films, inhibits the mTOR pathway and Th17 differentiation signaling to promote psoriasis resolution." (PMID 37495626, 2023). "Taken together, AOA can reduce the production of Th17-mediated inflammatory factors and increase Foxp3+ Tregs by inhibiting both activated serine metabolism and mTOR in the skin of a TPA-induced psoriasis mouse model." (PMID 37649889, 2023). "In agreement with our study, psoriatic skin-treated with ScF had a significantly low levels of mTOR protein alongside the downregulation of TNF-α, IL-1β, and IL-17 indicating an inhibitory effect of ScF on mTOR signaling to mitigate psoriasis severity." (PMID 37495626, 2023). "SAMHD1, C10orf99, and AKR1B10: the highly dysregulated genes in resolved epidermis are known to be associated with pathogenesis of psoriasis, and the DRTP was enriched in WNT, TNF, and mTOR signaling pathways." (PMID 36901987, 2023). "Several lines of evidence suggest that activated mTOR signaling seems to be involved in the pathogenesis of psoriasis through the upregulation of cell proliferation and secretion of inflammatory mediators." (PMID 37405259, 2023). "An analog of vitamin D 1α,25-dihydroxyvitamin D3-3-bromoacteate has been shown to inactivate Akt and eventually mTOR, resulting in decreased production of IL-22 and psoriasis-like characteristics." (PMID 37371141, 2023). "The metabolite was shown to directly inhibit mTOR, resulting in an increase in regulatory T-cells within the spleen, which decreased cutaneous psoriasis-like features and promoted healthy skin care." (PMID 37371141, 2023). "MTOR includes two complexes, mTOR complex 1 (mTORC1) and mTORC2, both of which are essential for the progression of psoriasis due to their function of regulating cell proliferation and inflammation." (PMID 38008779, 2023). "This decreased activation of mTOR by AOA suggests that psoriasis can be alleviated by normalizing the imbalance of Th17/Treg cells." (PMID 37649889, 2023). "PI3K/Akt/mTOR pathway activation was observed in human epidermal keratinocytes treated with F to simulate psoriasis-like disease, inducing differentiation and inhibiting interleukin-22-induced proliferation, as well as activating the PI3K/Akt/mTOR pathway." (PMID 37174126, 2023). "It has been shown that IL-17A-activated PI3K/AKT/mTOR signaling contributed to the inflammatory response of psoriasis partly by inhibiting autophagy in keratinocytes." (PMID 36937834, 2023). "Erianin has been shown to possess anti-tumor and anti-psoriasis activity partly by suppressing the Akt/mTOR pathway." (PMID 37371141, 2023). "Deregulated PI3K/Akt/mTOR signaling has been shown to impact both the structural skin barrier components as well as inflammatory disease components of psoriasis." (PMID 37371141, 2023). "Both IL-17A and ROS were found to stimulate the activation of the NF-κB and PI3K/AKT/mTOR signaling pathways involved in the pathogenesis of psoriasis." (PMID 36498953, 2022). "AKT/mTOR signaling participates in the progression of psoriasis and tunes the fate of T cell by HIF-1α-mediated glycolysis." (PMID 35296088, 2022). "Rapamycin, a mTOR inhibitor, has been used in few patients with psoriasis due to its antiproliferative and immunosuppressive actions." (PMID 35265634, 2022). "Gene ontology analysis revealed enriched functional groups related to PI3K/Akt/mTOR signaling pathways, psoriasis, and epidermal development." (PMID 36741386, 2022).